ANGPTL4 (angiopoietin like 4)
Diseases named in the same sentence as ANGPTL4 in open-access papers (continued):
Sharing a sentence is not in itself a finding about the gene and the disease.
melanoma (continued). "Since ANGPTL4 alters the migratory capacity of several cell types, we examined if ANGPTL4 over-expressing melanoma cells would manifest an altered ability to migrate through collagen coated transwells." (PMID 29100268, 2017). "Whereas ANGPTL4 enhanced TEM of cutaneous melanoma cells through the blood brain barrier, it reduced TEM of the MBM cells through the blood brain barrier." (PMID 29100268, 2017). "The aim of this study was to determine the functional significance of ANGPTL4 in the shaping of melanoma malignancy phenotype, especially in the establishment of brain metastasis." (PMID 29100268, 2017). "The results demonstrated that like certain other genes, ANGPTL4 plays a yin-yang role depending on tumor stage; it promotes malignancy of cutaneous melanoma cells and ameliorates the malignant phenotype of brain-metastasizing cells." (PMID 29100268, 2017). "In vitro experiments indicated that brain-derived soluble factors and transforming growth factor β1 (TGFβ1) up-regulated ANGPTL4 expression by melanoma cells." (PMID 29100268, 2017). "In the next set of experiments we examined the effect of ANGPTL4 over-expression or knock-down on protein expression profile in melanoma cells." (PMID 29100268, 2017). "We also examined if ANGPTL4 down-regulation alters the ability of melanoma cells to migrate through collagen coated transwells." (PMID 29100268, 2017). "In an ongoing effort to identify molecular determinants regulating melanoma brain metastasis, we previously identified Angiopoietin-like 4 (ANGPTL4) as a component of the molecular signature of such metastases." (PMID 29100268, 2017). "These experiments lead us to conclude that a high expression of ANGPTL4 in the cutaneous cells sensitizes these melanoma cells to cytotoxicity mediated by BDF." (PMID 29100268, 2017). "Expression of ANGPTL4 in the MBM cells protects these melanoma cells from death exerted by BDF, increasing their sustainability in the brain microenvironment." (PMID 29100268, 2017). "The question if and how ANGPTL4 is involved in the shaping of the in vivo malignancy phenotype of melanoma cells was examined." (PMID 29100268, 2017). "To investigate the involvement of ANGPTL4 in melanoma malignancy, we have established cutaneous and MBM cells in which ANGPTL4 is overexpressed and MBM cells in whom ANGPTL4 is knocked-down." (PMID 29100268, 2017). "This suggests that ANGPTL4 contributes to melanoma cell invasion from the primary tumor to enhance metastatic spread." (PMID 29100268, 2017). "Taken together these results indicated that ANGPTL4 is a determinant of the adherence capacity of melanoma cells to BEC." (PMID 29100268, 2017). "In the future we plan to identify the active factors in the BDF, that affect melanoma cell viability and other observed phenomena (i.e. ANGPTL4 expression)." (PMID 29100268, 2017). "Cancer cells, including melanomas, tend to selectively utilize the beneficial functions of TGFβ signal transduction, including ANGPTL4 up-regulation (via the Smad signaling pathway), while eliminating the tumor suppressor function downstream to TGFβ." (PMID 29100268, 2017). "The results suggest that ALDOA is a critical mediator of the promoting effect of ANGPTL4 on melanoma cell invasion, likely through upregulating the MMP-2 expression." (PMID 24959248, 2014). "In the present study, the association between angiopoietin-like 4 (ANGPTL4) and aldolase A (ALDOA) in human melanoma cell invasion and survival was investigated." (PMID 24959248, 2014). "A recent study has shown that ANGPTL4 is highly expressed in melanoma brain metastasis and micrometastasis cells, suggesting that ANGPTL4 is involved in melanoma metastasis." (PMID 24959248, 2014). "Our laboratory has previously shown that ANGPTL4 prevents metastases by inhibiting vascular permeability as well as tumor cell motility and invasiveness in a model of xenografted melanoma B16F0 cells." (PMID 20454689, 2010).
melanoma (continued). "Possibly related to its capacity to disrupt the integrity of the BBB, we found that ANGPTL4, a marker of human melanoma brain metastasis whose expression is regulated by TGFβ1,177 promotes the malignancy of cutaneous melanoma cells and augments their potential to form brain metastasis." (PMID 32761606, 2021). "Conversely, murine melanoma or lung cancer cells transfected with full-length ANGPTL4 and injected subcutaneously to syngeneic mice decreased lung and brain metastatic dissemination, suggesting a protective effect of ANGPTL4 on lung microvascular disruption." (PMID 32405335, 2020). "ANGPTL-4 requires upregulation by TGFβ in many cancers including melanoma metastasis to the brain." (PMID 33139674, 2020). "This might be critical to develop ANGPTL4-targeted or proteoglycan-targeted strategies against adaptive resistance in melanoma therapy." (PMID 33196458, 2020). "This may imply that EMT constitutes a mechanism by which ANGPTL4 is involved in melanoma progression." (PMID 29100268, 2017). "We therefore evaluated whether ANGPTL4 affecs the transendothelial migration (TEM) of melanoma cells in a blood-brain barrier (BBB) model simulating the extravasation of melanoma cells through BEC towards astrocytes." (PMID 29100268, 2017). "A similar mechanism may operate in the case of MBM, as we have demonstrated that ANGPTL4 increases the ability of melanoma cells to penetrate brain endothelial cell monolayer." (PMID 29100268, 2017). "This suggests that ANGPTL4 contributes to melanoma cell passage through BBB junctions." (PMID 29100268, 2017). "Interestingly, RPPA analysis of high vs. low ANGPTL4 expressing melanoma cells demonstrated that most differentially expressed proteins are either up-stream or down-stream of the EMT cascade, which is classically controlled by the TGFβ pathway." (PMID 29100268, 2017). "Identifying the differentially expressed proteins may highlight the mechanism by which ANGPTL4 regulates the malignancy phenotype of melanoma cells." (PMID 29100268, 2017). "In order to test whether the brain microenvironment modulates the expression of ANGPTL4 in melanoma cells, melanoma cells were subjected to BDF for 24 hrs, and then tested for ANGPTL4 expression." (PMID 29100268, 2017). "We next examined if ANGPTL4 down-regulation in melanoma cells affects MMP-2 secretion." (PMID 29100268, 2017). "The results suggest that ANGPTL4 expression may affect ALDOA expression in human melanoma cells at the gene transcription level through a PKC-dependent mechanism." (PMID 24959248, 2014). "In the present study, ALDOA expression at both the mRNA and the protein levels was significantly increased and decreased in parallel with overexpression and knockdown of ANGPTL4 in melanoma cells, which was blocked by selective PKC inhibitor and restored by PKC agonist, respectively." (PMID 24959248, 2014). "To determine whether ANGPTL4 regulates ALDOA expression in human melanoma cells by altering the ALDOA gene promoter activity, we transfected WM-115 and WM-266-4 cells with human ALDOA promoter-luciferase reporter plasmids." (PMID 24959248, 2014). "Luciferase assays confirmed that ANGPTL4 could enhance ALDOA gene promoter/transcriptional activities in melanoma cells through a PKC-dependent mechanism." (PMID 24959248, 2014). "Additionally, our results also suggest that ALDOA plays an important role in ANGPTL4-enhanced melanoma cell survival against cisplatin-induced apoptotic stress, which implicates ANGPTL4 and ALDOA in the development of melanoma chemoresistance." (PMID 24959248, 2014). "The role of ANGPTL4 protein in drug-selected melanoma cells might be important." (PMID 33196458, 2020). "Various studies have also shown that ANGPTL4 expression prevents metastasis and angiogenesis by reducing vascular leakiness, cell motility and invasiveness in different neoplasm types, including melanoma, gastric, lung and colorectal tumors, as well as metastases." (PMID 32928141, 2020).
melanoma (continued). "A previous study suggested that ANGPTL4 may promote melanoma metastasis." (PMID 24959248, 2014). "We show that ANGPTL4 is very strongly correlated with hypoxia in RCC, Melanoma, NSCLC, BRCA, GBM, and head and neck squamous cell carcinoma." (PMID 40233044, 2025). "Spatial single-cell RNA sequencing indicates that pericytes up-regulate ANGPTL4 and SERPINE1 near melanoma cell aggregates, suggesting that they are involved in the generation of a pseudo-stem niche." (PMID 41463339, 2025). "In our selected subpopulation with high ANGPTL4 expression, we did see reduced ERK phosphorylation comparing with that of parental melanoma cells." (PMID 33196458, 2020). "This demonstrates a regulatory function for INHBA, FABP7, ANGPTL4, and CYR61 in melanoma cell migration." (PMID 29454361, 2018). "Next, we investigated a possible impact of the four selected genes (INHBA, FABP7, ANGPTL4, and CYR61) on overall survival of melanoma patients." (PMID 29454361, 2018). "In a next step, we down-regulated the four selected genes above (INHBA, CYR61, ANGPTL4, andFABP7) using siRNA in SKMEL28 cells to analyze their possible influence on melanoma cell adhesion and migration." (PMID 29454361, 2018). "The results not only suggest an important functional role of ALDOA in ANGPTL4-enhanced melanoma cell survival, but also implicate ANGPTL4 and ALDOA in the development of melanoma chemoresistance." (PMID 24959248, 2014). "Since our findings had suggested that ALDOA was a downstream effector of ANGPTL4/PKC signaling, we investigated the functional roles of ANGPTL4 and ALDOA in melanoma cell invasion." (PMID 24959248, 2014). "Therefore, to elucidate the unidentified effects of the antidiabetic regents, FABP5, ANGPTL4 and/or MITF on diabetic states of MM, high-glucose-induced metabolic and redox alterations were studied using melanoma A375 cells." (PMID 39940783, 2025). "The down-regulation of INHBA, CYR61 and ANGPTL4, which was found in SKMEL28 melanoma cells after treatment with Wnt3a-CM could be confirmed in these four cell lines by real-time qPCR when compared to the 3T3-CM samples." (PMID 29454361, 2018). "To investigate the functional roles of ANGPTL4 and ALDOA in melanoma cell survival against apoptotic stress, we examined cell apoptosis in melanoma cells treated with 10 nM of cisplatin, an apoptosis-inducing chemotherapeutic agent commonly used to treat melanoma." (PMID 24959248, 2014). "Additionally, our results suggest that ALDOA plays an important role in ANGPTL4-enhanced melanoma cell survival against apoptotic stress, which implicates ANGPTL4 and ALDOA in the development of melanoma chemoresistance." (PMID 24959248, 2014). "It remains unclear whether ANGPTL4 and ALDOA may impact melanoma cell survival against other types of chemotherapy agents." (PMID 24959248, 2014). "To examine the functional roles of ANGPTL4 and ALDOA in melanoma cell invasion, we performed in vitro cell invasion assays, which showed that ANGPTL4 overexpression increased cell invasion in WM-115 cells by over two-fold, which was reversed by knocking down ALDOA." (PMID 24959248, 2014). "In order to find out whether ANGPTL4 levels play a role in the differential susceptability of the cutaneous and MBM cells to these soluble factors, we examined the effect of BDF on the viability of melanoma cells, expressing high or low levels of ANGPTL4." (PMID 29100268, 2017). "In addition, although it has been reported that activation of PKC can induce ANGPTL4 expression in human airway smooth muscle cells, our data indicate that PKC does not modulate ANTPTL-4 expression in melanoma cells." (PMID 24959248, 2014).
gastric cancer (30 papers, 2008 to 2025). A primary or metastatic malignant neoplasm involving the stomach. "Along with that, HIF-1 induced ANGPTL4 appears to promote anoikis resistance and tumor growth in scirrhous gastric cancer." (PMID 40233044, 2025). "In connection to fibroblast, prior investigation revealed elevated Angptl4 expression in CAFs of breast, gallbladder, and gastric cancer." (PMID 39811640, 2025). "In gastric cancer, Okochi-Takada and colleagues revealed that ANGPTL4 is a genetically and epigenetically inactivated secreted tumor suppressor in cancer angiogenesis." (PMID 38212795, 2024). "ANGPTL4 also promotes tumor growth and enhances anoikis resistance in the scirrhous gastric cancer cells and the head and neck squamous carcinoma cells." (PMID 38345559, 2024). "In cancer studies, the effect of ANGPTL4 on angiogenesis appears to be dual and contradictory, especially in gastric cancer and OC." (PMID 38212795, 2024). "On the other hand, we have observed the upregulation of genes that are involved in the proliferation, migration, and invasion of cancer cells in colorectal and gastric cancer (ANGPTL4, S100A8, LINC00668)." (PMID 35625760, 2022). "Our integrated bioinformatics analysis further demonstrated the complexity of ANGPTL4’s role in gastric cancer." (PMID 32410376, 2020). "ANGPTL4 mRNA has been found to be upregulated in the perinecrotic areas of many human tumors, renal carcinomas, squamous cell carcinomas, and gastric cancers." (PMID 33196458, 2020). "Qian and his colleagues demonstrated that LMX1A represses C-MYC expression by activating ANGPTL4 to function as a tumor suppressor in gastric cancer." (PMID 32751497, 2020). "Further, we investigated the relationship between LMX1A and ANGPTL4 in clinical gastric cancer samples by using The Cancer Genome Atlas (TCGA) Stomach Adenocarcinoma data collection." (PMID 31557193, 2019). "As only ANGPTL4 was verified to be consistently up-regulated by LMX1A in two gastric cancer cell lines, we chose ANGPTL4 for further functional analysis." (PMID 31557193, 2019). "In N+ gastric cancer, leptin-induced phosphorylation of angiopoietin-like protein 4 (ANGPTL4) enhances lipid uptake via overexpressed lipoprotein lipase (LPL), thereby stimulating prostaglandin E2 (PGE2) production and ultimately facilitating lymph node metastasis." (PMID 40977700, 2025). "Studies have shown that ANGPTL4 might have anti-angiogenic and anti-metastatic effects on gastric cancer through the down-regulation of ERK and epigenetic inhibition." (PMID 36447119, 2023). "Knockdown of ANGPTL4 inhibits the development of human gastric cancer." (PMID 34540685, 2021). "Moreover, the secreted protein angiopoietin-like-4 (ANGPTL4), which is induced by hypoxia, exerts various effects on the neoplastic progression in scirrhous gastric carcinoma." (PMID 32326163, 2020). "ANGPTL4 was found to promote gastric cancer proliferation and metastasis." (PMID 31847905, 2019). "We confirmed that the expression of LMX1A was indeed dramatically reduced in gastric cancer samples compared to health group samples, following decreased ANGPTL4 expression, which suggested the positive-regulatory relationship between LMX1A and ANGPTL4 also existed in gastric cancer samples." (PMID 31557193, 2019). "Both LMX1A and ANGPTL4 showed downregulated expression in gastric cancer samples." (PMID 31557193, 2019). "Since LMX1A was proved to contribute to ANGPTL4 expression in gastric cancer cells, it was concerned whether up-regulation of ANGPTL4 could also influence the tumor suppression role of LMX1A." (PMID 31557193, 2019). "Considering LMX1A as a transcription factor, we proposed that LMX1A could contribute to the ANGPTL4 expression and inhibit tumor growth in gastric cancer." (PMID 31557193, 2019).
gastric cancer (continued). "This variability is a common characteristic of hypoxic secreted factors, as levels of induction will be determined by differences in both cell genotype and expression levels of regulatory enzymes, and is also evident for ANGPTL4 in gastric cancer and uveal melanoma cell lines." (PMID 29739381, 2018). "ANGPTL4 levels were higher in SGC cells under hypoxia than in other types of gastric cancer cells." (PMID 28894280, 2017). "Moreover, a finding in gastric cancer has suggested that methylation is a mechanism of silencing ANGPTL4 gene leading to tumor development." (PMID 25148701, 2014). "Thus, our results showed an upregulation of LMX1A is related with increased ANGPTL4 expression in gastric cancer cells, which could further contribute to the gastric tumor growth inhibition." (PMID 31557193, 2019). "In gastric cancer, we found CTHRC1 was highly co-expressed with many factors, such as ACVRL1, ANGPTL3, ANGPTL4, NOTCH4, VEGFB, VEGFC etc., which have been proved to play an important role in angiogenesis in various cancer." (PMID 35928443, 2022). "Angiopoietin-like-4 (ANGPTL4), a secreted protein essential for tumor growth and resistance to anoikis in gastric cancer cells, is also upregulated by HIF-1α." (PMID 32780245, 2020). "In this study, by identifying LMX1A-regulated genes using RNA sequencing in gastric cancer cell lines, we show that LMX1A exerts its tumor suppressive role partly through up-regulating ANGPTL4." (PMID 31557193, 2019). "More importantly, the expression of LMX1A is positively correlated with ANGPTL4, without including other family members in gastric cancer cell lines." (PMID 31557193, 2019). "Additionally, a report showed that ANGPTL3 and ANGPTL6 expression was lower in gastric cancer (GC) tissues compared to normal gastric tissues, while ANGPTL1, ANGPTL2, and ANGPTL4 were more highly expressed in GC tissues than in normal gastric tissue." (PMID 39708716, 2025). "Indeed, ANGPTL4, but not six other ANGPTL family members, showed co-expression with LMX1A in gastric cancer samples." (PMID 31557193, 2019).